IGF1 (insulin like growth factor 1)
Diseases named in the same sentence as IGF1 in open-access papers (continued):
Sharing a sentence is not in itself a finding about the gene and the disease.
congenital heart disease (7 papers, 2021 to 2025). A heart disease that is present at birth. "Unlike Noonan syndrome (PTPN11 mutations), ZNF292 cases rarely exhibit facial dysmorphism or congenital heart disease, while their normal IGF‐1 levels distinguish them from GH deficiency." (PMID 40777882, 2025). "IGF-1 is an essential regulator of cardiac structure and homeostasis and reduced serum levels of IGF-1 are found in patients with cyanotic congenital heart disease, who experience chronic hypoxemia." (PMID 35731367, 2022). "Increased myocardial expression of myostatin was noted in congenital heart disease, and an increase in the ratio of myostatin to insulin-like growth factor 1 correlated with worsening of LV function." (PMID 34479416, 2021). "The data suggest that miR-486-5p may have a pathological role in cyanotic congenital heart disease by targeting IGF-1, thereby promoting cardiomyocyte apoptosis." (PMID 35731367, 2022). "Moreover, miR- 499 and miR-1275 may play a significant role in cardiac muscle mitochondrial functioning whereas miR-23b via targeting the GATA6/IGF-1 axis may promote congenital heart disease development." (PMID 38256030, 2024).
emphysema (7 papers, 2009 to 2025). "Our findings demonstrate that HHIP drives myofibroblast transition, inhibits epithelial stem/progenitor cell senescence, and guards against BPD and BPD-associated emphysema via suppressing Hh-IGF1 signaling axis." (PMID 40333979, 2025). "Increased Igfbp3 expression is associated with emphysema and senescent fibroblasts, where it results in Igf1 sequestration and reduced cell proliferation." (PMID 19804646, 2009). "Our study highlights that antagonizing the Hh-IGF1 signaling pathway is a potential targeted therapeutic strategy for BPD and BPD-associated COPD/emphysema." (PMID 40333979, 2025). "Using a transgenic mouse deficient for p16, we demonstrated that lungs of mice lacking p16 were structurally and functionally resistant to CS-induced emphysema due to activation of IGF1/Akt regenerative and protective signaling." (PMID 31428695, 2019). "UA reduced EMT, EndMT, airway-vessel remodeling, and musculi soleus atrophy in CS-induced emphysema model rats at least partly through IGF1 and TGF-β1/Smad2.3 signaling pathways." (PMID 31170951, 2019). "In conclusion, our study suggests that targeting senescence may facilitate alveolar regeneration in COPD emphysema by promoting IGF1 proliferative signaling." (PMID 31428695, 2019). "Moreover, CS-exposed p16−/− mice exhibit normal pulmonary function, reduced emphysema, and increased insulin-like growth factor 1 (IGF1) signalling, suggesting that targeting senescence may facilitate alveolar regeneration in COPD." (PMID 35749794, 2022). "Therefore, we used CS induced rat emphysema model to assessed the effect of UA on EMT, EndMT, airway-vessel remodeling and muscle consumption and discuss the underlying mechanisms through TGF-β1/Smads pathways and IGF1 molecule." (PMID 31170951, 2019). "However, whether UA can alleviate CS-induced airway remodeling and muscle consumption in emphysema rats, and whether UA exerts its effects through TGF-β1/Smads and IGF1 pathways, remains to be established." (PMID 31170951, 2019).
esophageal squamous cell carcinoma (7 papers, 2015 to 2025). Esophageal squamous cell carcinoma (ESCC) is a type of esophageal carcinoma (EC) that can affect any part of the esophagus, but is usually located in the upper or middle third. "Additionally, targeting the IGF-1/IGF-1R-FOXC1-IGF-1R loop emerges as a promising therapy for anti-cancer stem cell therapy in esophageal squamous cell carcinoma." (PMID 38413558, 2024). "Studies reveal that HIF-1α upregulates insulin-like growth factor 1 (IGF1) secretion, which sustains the self-renewal capacity and stemness features of esophageal squamous cell carcinoma (ESCC) stem cells, ultimately promoting therapeutic resistance and tumor recurrence." (PMID 40755775, 2025). "This establishes a significant positive feedback loop (IGF-1/IGF-1R-FOXC1-IGF-1R), underscoring FOXC1’s potential role as a prognostic biomarker for esophageal squamous cell carcinoma." (PMID 38413558, 2024).
Failure to thrive (7 papers, 2012 to 2025). Failure to thrive (FTT) refers to a child whose physical growth is substantially below the norm. "We find that Zcchc11 is widely expressed across multiple tissues shortly after birth and that in neonatal mice Zcchc11 deficiency results in a failure to thrive, associated with diminished IGF-1 expression." (PMID 23209448, 2012). "This study underscores the critical role of miR-137 in failure to thrive through regulation of the GH/IGF-1 axis and supports the use of MiR137−/− as a disease model for GH resistance." (PMID 40598150, 2025). "The pathophysiology of failure to thrive (FTT) due to ATH includes low calorie intake, increased energy requirements associated with labored breathing, hypoxemia, and interruption of growth hormone–insulin-like growth factor-1 (GH-IGF-1) axis secretion." (PMID 27738609, 2016).
helminth infection (7 papers, 2014 to 2023). "On the other hand, wound healing associated genes such as igf-1 encoding Insulin-like growth factor 1 suggested to be involved in resolving tissue damage following helminth infection, and fn1 encoding fibronectin produced during the resolution of tissue damage were both highly up-regulated." (PMID 27505056, 2016). "The impact of IGF1 in a more chronic setting or in the context of the small intestine during a helminth infection has yet to be assessed." (PMID 36569914, 2022). "The effect of helminth infection on lower free IGF-1 level seemed to be partly mediated through BMI, as adjustment for BMI, attenuated the differences between two groups although remaining significant." (PMID 33149205, 2020). "Here, we assessed the impact of helminth infection on free IGF-1 and its major binding protein, IGFBP-3, in adults." (PMID 33149205, 2020). "To address this, we conducted a study in the adult population living in an area endemic for helminth infection to evaluate the association between STH infections and free IGF-1 concentration as well as its main binding protein, IGFBP-3." (PMID 33149205, 2020). "IGF1 has also been reported to influence activation of macrophages in response to high-fat diet or helminthic infection." (PMID 31035605, 2019). "Another mechanism by which helminth infection could affect serum free IGF-1 levels might be mediated by insulin." (PMID 33149205, 2020). "When using PCR to detect helminth infection, we found a significantly lower serum free IGF-1 among STH-infected compared to uninfected subjects [− 0.090 (− 0.132; − 0.048), P < 0.001] and this did not change following adjustment with age and sex [− 0.89 (− 0.125; − 0.053), P < 0.001]." (PMID 33149205, 2020). "Our study showed that helminth infection in adults is associated with lower free IGF-1 levels but not with IGFBP-3 and albendazole treatment significantly increases free IGF-1 levels in the study population." (PMID 33149205, 2020). "There are several possibilities as to how helminth infection could decrease serum free IGF-1 level." (PMID 33149205, 2020). "The observation regarding decreasing levels of IGF-1 with an increasing number of helminth infections in this study might suggest more disruption of nutrient intake, which in turn could directly or indirectly be linked to changes in the BMI and fasting insulin level." (PMID 33149205, 2020). "Helminth infection induces a Th2 immune response to produce high levels of Arg-1, TGF-β, vascular endothelial growth factor (VEGF), YM1, and insulin-like growth factor-1 (IGF-1) to inhibit parasitic confinement and clearance." (PMID 38274792, 2023). "Subsequently, to assess causality, we investigated the effect of anthelmintic treatment on serum free IGF-1 and IGFBP-3 levels to evaluate the effect of helminth infections on IGF system." (PMID 33149205, 2020). "IL-4 and IL-13 were shown previously to induce the expression of macrophage IGF-1 and coincident expression of type 2 cytokines and IGF-1 was demonstrated in experimental helminth infection." (PMID 24967908, 2014). "When helminth infection was detected based on microscopy, a less sensitive method that misses infection in 10.3% of the subjects, the difference in the level of free IGF-1 and IGFBP-3 between STH-infected and non-infected subjects fell short of statistical significance." (PMID 33149205, 2020).
Hyperkeratosis (7 papers, 2016 to 2025). Hyperkeratosis is a histopathological term defining a thickened stratum corneum and may be present in many different skin conditions, with many possible overlaps. "In addition, persistent overexpression of IGF-1 leads to epidermal hyperplasia, hyperkeratosis and cutaneous tumorigenesis, identifying the high concentration of IGF-1 resulting in the malignant behaviour of skin papillomas." (PMID 35741452, 2022). "Reduced IGFBP-1 and IGFBP-2 levels could increase free IGF-1, thereby promoting the development of papillomatosis and hyperkeratosis observed in AN." (PMID 29706998, 2018). "Moreover, research using IGF-1 transgenic mice showed that IGF-1 overexpression in the basal layer of the epidermis resulted in epidermal hyperplasia and hyperkeratosis." (PMID 27190511, 2016).
hyperuricemia (7 papers, 2014 to 2025). An abnormally high level of uric acid. "After controlling for confounding factors, subjects with hyperuricemia maintained higher levels of IGF-1 and lower eGFR compared to those with normal acid uric levels." (PMID 29505614, 2018). "Results from logistic regression model showed that peak GH were negatively associated with hyperuricemia after controlling for age, gender, tanner stage, BMI SDS, IGF-1, blood pressure, HOMA-IR, lipids status." (PMID 29785038, 2018). "Notably, peak stimulated GH was significantly associated with hyperuricemia after controlling for age, gender, tanner stage, BMI SDS, IGF-1, blood pressure, HOMA-IR, lipids status for overall model (OR0.689, 95% CI 0.503–0.944; P = 0.02)." (PMID 29785038, 2018). "Subjects with hyperuricemia were older, had higher BMI, BMI SDS, waist circumference, SBP, DBP, triglycerides, ALT and IGF-1 levels and lower HDL-cholesterol, AST, AST to ALT ratio, eGFR and u-ACR compared with those with normal acid uric levels." (PMID 29505614, 2018).
kidney injury (7 papers, 2014 to 2025). Trauma to the kidney. "Insulin-like growth factor-1 (IGF-1) plays an important protective role in the setting of kidney injury." (PMID 36622388, 2023). "MSCs can also produce IGF-1, while administration of IGF-1 gene-silenced MSCs limits their protective effect on renal function and tubular structure in murine cisplatin-induced kidney injury, indicating that MSCs exert their beneficial effects by producing IGF-1." (PMID 25158205, 2014). "It is well recognized that MSCs can secrete a broad range of trophic factors, such as HGF, bFGF, IGF-1, and EGF, all known to improve the renal function in animal models of kidney injury, due to their antiapoptotic, mitogenic, and morphogenic activities on intrarenal cells." (PMID 26167475, 2015).
lipodystrophy (7 papers, 2015 to 2025). A congenital or acquired disorder characterized by abnormal loss or redistribution of the adipose tissue in the body. "Dysregulation of IGF1 also contributes to metabolic syndromes and lipodystrophy in these individuals." (PMID 25890304, 2015). "Our findings, in conjunction with existing literature, suggest that monitoring IGF-1 levels may offer additional insights into the effectiveness of leptin replacement therapy in managing lipodystrophy and related metabolic complications." (PMID 40520449, 2025). "Since caveolae constitute one pathway for the internalization of GH in vitro, the elevated growth velocity and IGF-1 levels, observed in our children with CGL4, could be associated with the reducing caveolae formations, typical of this subtype of lipodystrophy, since GH pulsatility was normal." (PMID 37501786, 2023). "Low levels of IGF-1 have previously been reported in patients with FPLD and other forms of lipodystrophy." (PMID 40520449, 2025).
migraine (7 papers, 2021 to 2025). "While other emerging therapies—such as IGF-1 application, sealing of the round window, and migraine prophylaxis—show encouraging preliminary results, they require further validation through robust, randomized trials." (PMID 40734818, 2025). "Emerging therapies, such as intranasal insulin-like growth factor 1 administration, epigenetic modulators, and vagus nerve stimulation, offer promising avenues for reducing CSD susceptibility and migraine frequency." (PMID 39456943, 2024). "These include standard intratympanic corticosteroids (ITS), hyperbaric oxygen therapy (HT), novel pharmacologic agents [e.g., insulin-like growth factor 1 (IGF-1), diuretics, urokinase, and migraine medications], surgical approaches, and targeted drug delivery systems." (PMID 40734818, 2025). "In addition, insulin-like growth factor-1 (IGF-1) treatment can inhibit CSD and calcitonin-gene-related peptide (CGRP) production, thereby relieving migraine-related hyperalgesia." (PMID 34325647, 2021).
nonalcoholic steatohepatitis (7 papers, 2022 to 2024). "Similar findings were observed in an IGF-1-treated nonalcoholic steatohepatitis mouse model." (PMID 35203722, 2022).
oral cancer (7 papers, 2017 to 2024). "It was previously demonstrated that blood IGF-1 was reduced in oral cancer, cancer cachexia, and fasting." (PMID 36980729, 2023). "However, in line with our findings, lower serum levels of IGF-1 have been reported in oral cancer patients compared to healthy controls." (PMID 28143425, 2017). "The FaDu cells were treated with NVP‐AEW541 (IGF‐IR inhibitor) to disrupt the IGF‐1 signalling to examine the role of IGF‐1 in inducing EMT and invasion in oral cancer cells." (PMID 34528373, 2021). "They reported alterations in parameters such as matrix metalloproteinases 2 and 9, IGF-1, and sIgA in the saliva and demonstrated a significant increase in salivary LDH level of oral cancer patients, which was in agreement with the current results." (PMID 33167957, 2020). "Mechanistically, it has been shown that treatment of oral cancer cells with inhibitors of MAPK and PI3K impaired IGF1-induced repression of miR-99a." (PMID 28708091, 2017). "IGF‐1, which is secreted in OSF, promoted the migration ability in oral cancer cells." (PMID 34528373, 2021). "Thus, IGF‐1 was elevated in OSF and, consequently, increased the expression of IGF‐IR and promoted the EMT and invasion by upregulating IGF‐1R in human oral cancer." (PMID 34528373, 2021).
pancreatitis (7 papers, 2011 to 2025). Inflammation of the pancreas. "The main production sources of IL-10 are T-helper, monocyte, macrophage, and dendrite cells, and plasma increases IL-10 levels in the organism in the IGF-1 administration without the formation of pancreatitis." (PMID 37763806, 2023).
periodontal disease (7 papers, 2012 to 2025). "The severity of periodontal disease was also higher in acromegalic patients with higher IGF-1 levels." (PMID 35285598, 2022). "The ANOVA test showed a statistically significant difference (p=0.041) in concentration of IGF-1 levels in stage I based on severity of periodontal disease." (PMID 35285598, 2022). "NGAL expression can be stimulated by many cytokines and growth factors that may contribute to periodontal diseases, such as interleukin-1, IL-17, IL-22, insulin-like growth factor-1, transforming growth factor alpha, and tumor necrosis factor-alpha." (PMID 41040472, 2025). "In this study, IGF-1 varied based on periodontal disease severity." (PMID 35285598, 2022). "Therefore, the present study aimed to evaluate salivary IGF-1, IGFBP-3, and CTX among children, adolescents, and younger adults and to determine the association of these markers among the study population with different chronological age groups with and without periodontal disease." (PMID 36138609, 2022). "The prime objective of this study was to estimate the salivary levels of IGF-1, IGFBP-3, and CTX among the participants with and without periodontal disease belonging to the different skeletal maturity groups, categorised according to cervical vertebrae staging criteria." (PMID 35285598, 2022).
pituitary dwarfism (7 papers, 2016 to 2025). Proportionately decreased bodily growth due to failure of the pituitary gland to produce an adequate supply of growth hormone. "This is probably caused by a deficiency of insulin-like growth factor 1 (IGF-1) and is also known as “pituitary dwarfism”." (PMID 37238915, 2023). "Such alteration presented with normal‐high basal GH and low IGF‐1 1 contrary to pituitary dwarfism (or Growth Hormone Deficiency – GHD) which presented both IGF‐1 and GH low serum levels." (PMID 29152285, 2017). "This pig breed shows a form of miniaturization called “proportional dwarfism” which Simianer and Köhn suggested to be a form of pituitary dwarfism, caused by lower secretion of growth hormones from the pituitary gland, leading to a decreased secretion of the insulin-like growth factor 1 (IGF1)." (PMID 30231878, 2018). "In conclusion, patients with IGF‐1 deficiency tend to be misdiagnosed with pituitary dwarfism." (PMID 29152285, 2017). "Hyposomatotropism or pituitary dwarfism is a very rare condition in cats, where IGF-1 concentrations are expected to be low or undetectable." (PMID 37756097, 2023). "Patient P3, carrying the novel c.557T>G p.(Leu186Arg) variant, was diagnosed in the neonatal period with symptoms including constipation, prolonged neonatal jaundice, pituitary dwarfism, anterior pituitary hypoplasia, and low levels of IGF1, TSH, FT4, GH, and PRL." (PMID 40141050, 2025).
prostatic hyperplasia (7 papers, 2011 to 2026). "In this case, with the connection to gut IGF-1, the authors suggested that optimal diets and/or nutritional supplementation may ameliorate prostate disorders including BPH and prostate cancer." (PMID 36982560, 2023). "Actual evidence supports the possible involvement of GH/IGF1 in the pathogenesis of BPH and PCa also in the general population and therapeutic agents targeting the IGF1R may be beneficial in the treatment of prostate diseases." (PMID 33692752, 2021). "Thus, the relationship between IGF-1, insulin and BPH appears certain based upon the various journal reports and clinical investigations, which points to potential ways to therapeutically confront prostate disorders." (PMID 36982560, 2023).
retinal diseases (7 papers, 2018 to 2025). "The IGF-1 homologue, IGF-2, also binds to IGF-1R, however IGF-1 has closer associations with retinal disease and its influence on glucose metabolism is better characterised." (PMID 39433211, 2025). "By addressing these aspects, this review aims to assist readers in designing specific experiments to better comprehend how IGF-1 signals are altered in retinal diseases." (PMID 38300646, 2024). "In conclusion, PKM2 plays a pivotal role in the modulation of RPE metabolism and redox balance and could explain the mechanisms through which IGF-1 participates in the pathogenesis of some retinal diseases." (PMID 39769402, 2024). "These dynamics confirm that PKM2 plays a pivotal role in the modulation of RPE metabolism and redox balance and could explain the mechanisms through which IGF-1 participates in the pathogenesis of retinal diseases." (PMID 39769402, 2024). "In this review, we provide recent insights of inflammation as a common feature of retinal diseases (AMD, RP and RD) highlighting the role of microglia, exosomes and IGF-1 in this process." (PMID 30026694, 2018).
retinal ischemia (7 papers, 2010 to 2023). A ischemic disease that involves the retina. "While in the second stage, retinal ischemia increases the level of HIF-1, which triggers increases of VEGF and IGF-1." (PMID 37587267, 2023).